FGF3 (fibroblast growth factor 3)
Diseases named in the same sentence as FGF3 in open-access papers (continued):
Sharing a sentence is not in itself a finding about the gene and the disease.
LAMM syndrome (4 papers, 2011 to 2023). "In our study, we identified a novel mutation in the FGF3 gene in a consanguineous Iranian family with three affected members which had identical LAMM syndrome features including HL, outer ear and teeth malformation." (PMID 36934406, 2023). "Here, using WES, we introduce c.45delC as a novel mutation in the FGF3 gene that co‐segregated with LAMM syndrome in a consanguineous Iranian family." (PMID 36934406, 2023). "This study is the first reported case of LAMM syndrome in Iran, and our data further broaden the spectrum of FGF3 gene mutations." (PMID 36934406, 2023). "Here, we report the first identified case of LAMM syndrome in Iran, and by identifying a frameshift variant in the first exon of the FGF3 gene, our result will help better clarify the phenotype–genotype relation of LAMM syndrome." (PMID 36934406, 2023). "Loss of function of the FGF3 protein, as indicated by animal studies, is responsible for symptoms of LAMM syndrome." (PMID 36934406, 2023). "Here we add to the pathogenic allelic heterogeneity of FGF3 by implicating one novel pathogenic variant in FGF3, which segregates with LAMM syndrome in an Iranian family." (PMID 36934406, 2023). "To date, 23 pathogenic and likely pathogenic variants in the FGF3 gene have been reported to be associated with LAMM syndrome in PubMed, Web of Science, ClinVar, and HGMD databases." (PMID 36934406, 2023). "Recessive mutations of fibroblast growth factor 3 (FGF3) can cause LAMM syndrome (OMIM 610706), characterized by fully penetrant complete labyrinthine aplasia, microtia and microdontia." (PMID 21306635, 2011). "Molecular modeling result suggests a less drastic effect of p.R95W on FGF3 function compared with known missense mutations detected in fully penetrant LAMM syndrome." (PMID 21306635, 2011). "LAMM syndrome co-segregated with recessive mutations of the gene encoding fibroblast growth factor 3 (FGF3; OMIM 164950) on chromosome 11q13.2-q13.3." (PMID 21306635, 2011). "A total of five Turkish families and one Saudi family segregating LAMM syndrome and recessive FGF3 mutations have been reported to date." (PMID 21306635, 2011). "In contrast, the p.G66C mutation detected in subjects with fully penetrant LAMM syndrome introduces a partially buried cysteine (Cys) residue in FGF3." (PMID 21306635, 2011). "Mutations observed in LAMM patients include missense, nonsense and small frameshifts suggesting that LAMM syndrome is caused by loss of FGF3 function although functional studies have not been done." (PMID 31336982, 2019). "Mice deficient for FGF3 do not model LAMM syndrome but rather have abnormal inner ears with variable penetrance and expressivity on a uniform genetic background." (PMID 21306635, 2011). "Our study confirms that at least some recessive mutations of FGF3 may not always result in fully penetrant LAMM syndrome." (PMID 21306635, 2011). "However, development in mice in the absence of Fgf3 is far more advanced than that generally observed in LAMM syndrome patients." (PMID 31336982, 2019).
leukoplakia (4 papers, 2013 to 2020). A white patch or plaque on a mucous membrane that cannot be characterized clinically or pathologically as any other disease. "miR-31* was negatively associated with recurrent/newly formed oral leukoplakias, and they hypothesized that miR-31* may play an important role during OL progression via the regulation of fibroblast growth factor 3 (FGF3)." (PMID 24260035, 2013). "For instance, miR-31 negatively controls oral leukoplakia progression through the regulation of fibroblast growth factor 3 (FGF3)." (PMID 27284551, 2016).
microtia (4 papers, 2016 to 2024). "This would be consistent with Fgf3 targeted mouse alleles, which model defects in human tooth and ear development where FGF3 mutations cause congenital deafness, microtia, and microdontia." (PMID 27144312, 2016). "This study showed different results from a previous study that found three genes most related to the development of microtia HOXA2, followed by FGF3 and TCOF1, the third most common genes." (PMID 38594752, 2024).
craniosynostosis (2 papers, 2024). Craniosynostosis is defined as the premature fusion of one or more cranial sutures leading to secondary distortion of skull shape resulting in skull deformities with a variable presentation. "In humans, duplication of the chromosomal 11q13 region, which includes FGF3 and FGF4 causes intellectual disability, craniosynostosis and microcephaly." (PMID 39372737, 2024). "Also in humans, constitutional increases in FGF3 and FGF4 have been associated with an increased risk of craniosynostosis, and FGF4 has been shown to be a negative prognostic indicator for a number of cancers due to its effect on tumor growth, angiogenesis, invasion and metastasis." (PMID 38397188, 2024).
diabetes (2 papers, 2024 to 2026). "FGF3 and FGF22 are not well studied in the context of cellular metabolism, although there is evidence implicating FGF3 in diabetes and its consequences, such as diabetic retinopathy." (PMID 41131959, 2026).
esophageal adenocarcinoma (2 papers, 2019 to 2020). A malignant tumor with glandular differentiation arising predominantly from Barrett mucosa in the lower third of the esophagus. "Use case – Esophageal adenocarcinoma with reported amplification ofCCND1,MAP2K1,RICTOR,FGF10,FGF19,FGF3,FGF4 andMCL1." (PMID 31608148, 2019).
gastric cancer (2 papers, 2012 to 2022). A primary or metastatic malignant neoplasm involving the stomach. "In human malignancies, amplifications of FGF3 and FGFR2 are linked to breast and gastric cancer." (PMID 35996584, 2022).
head and neck carcinoma (2 papers, 2017 to 2020). A carcinoma that arises from the head and neck region. "Frequent amplification of the Fgf3 gene has been found in human tumors including head and neck cancer and implicated for neoplastic transformation and tumor progression." (PMID 29073177, 2017). "Among them, Fgf3, a gene frequently amplified in head and neck cancer, showed most prominent and significant gene expression change (2.4× increases), despite the hypomethylation of Fgf3 was identified at >10kb upstream of transcription start site." (PMID 29073177, 2017). "Fgf3 has the most prominent gene expression changes among all the genes examined by RT-PCR and has been reported to be amplified in head and neck cancers." (PMID 29073177, 2017). "Amplification of Fgf3 gene has been found in human head and neck cancer and thus hypomethylation of Fgf3 may serve as a potential biomarker for early detection of OSCC." (PMID 29073177, 2017).
head and neck squamous cell carcinoma (2 papers, 2024 to 2025). A squamous cell carcinoma that arises from any of the following anatomic sites: lip and oral cavity, nasal cavity, paranasal sinuses, pharynx, larynx, and salivary glands. "In head and neck squamous cell carcinoma (HNSCC), amplification of 11q13, containing among others CCDN1, FGF3, and FGF19, is frequent and has been linked with a poor prognosis." (PMID 39324009, 2024). "Amplification of 11q13 (FGF3/4/19, CCND1) is frequently observed in head and neck squamous cell carcinoma (HNSCC)." (PMID 40974176, 2025).
melanoma (2 papers, 2019 to 2023). A malignant, usually aggressive tumor composed of atypical, neoplastic melanocytes. "Additionally, previous studies reported that other genes are frequently mutated in melanoma and other cancer types, including BRCA2 (9/112, 8%), LRP1B (9/112, 8%), MET (8/112, 7%), PRKDC (7/112, 6%), NOTCH4 (7/112, 6%), CCND3 (6/112, 5%), and FGF3/4/19 (6/112, 5%)." (PMID 37649078, 2023). "Genomic profiling of 23 available subjects also identified gene amplifications of cell cycle regulators (Cyclin D1, CDK4, or CDK6), fibroblast growth factors (FGF19, FGF3, and FGF4) and EMSY (a DNA repair inactivating gene) uniquely clustered in acral melanoma subjects in the study." (PMID 30642373, 2019).
meningioma (2 papers, 2022 to 2024). A generally slow growing tumor attached to the dura mater. "We also demonstrated that FGF3 is able to enhance proliferation of a meningioma cell line and its mRNA is detectable in a KLF4K409Q-mutated primary tumors." (PMID 35996584, 2022). "The relative impact of FGF3 on secretory meningiomas with KLF4 mutation remains unclear and deserves further study supported by a larger number of primary tumor samples." (PMID 35996584, 2022). "Further analysis of FGF3 mRNA in meningioma tissues revealed that five out of six samples with KLF4K409Q (M-030, M-048, M-066, M-068, and M-070) expressed FGF3 mRNA (5.2, 21.4, 83.3, 9.8, and 298.4 copies per 106 copies of GAPDH mRNA, respectively)." (PMID 35996584, 2022). "Lastly, we detected FGF3 mRNA in primary human meningeal cells expressing KLF4K409Q and in human meningioma tumor specimens with a TRAF7/KLF4-mutated genotype." (PMID 35996584, 2022). "To demonstrate that FGF3 is expressed in KLF4K409Q-harboring meningiomas, we examined primary meningioma tumors available at the OUHSC tissue bank." (PMID 35996584, 2022). "Because a KLF4K409Q mutation occurs exclusively in meningiomas harboring a missense TRAF7 mutation, the significance of FGF3 expression should be studied in the context of TRAF7 neomorphic function." (PMID 35996584, 2022). "In our studies, no meningiomas had detectable levels of FGF3 mRNA, except for tumors carrying mutations in TRAF7 and KLF4." (PMID 35996584, 2022). "After we established that KLF4K409Q could induce expression of FGF3 in nonmeningioma cell lines, we examined whether it can also activate FGF3 transcription in a representative meningioma cell line HBL-52." (PMID 35996584, 2022). "Furthermore, FGF3 promotes proliferation of human meningioma cell lines." (PMID 35996584, 2022). "Indeed, recombinant FGF3 enhanced proliferation of a meningioma cell line in vitro." (PMID 35996584, 2022). "In this study, we prosecuted FGF3, the top KLF4K409Q-upregulated gene, and demonstrated its ability to contribute to meningioma growth." (PMID 35996584, 2022). "Among other targets, this leads to the transcriptional activation of fibroblast growth factor 3 (FGF3) expression in KLF4-K409Q-expressing cells, not present in wild-type KLF4-expressing cells, and KLF4-K409Q-mutated meningiomas expressed higher levels of FGF3 compared to KLF4-wild-type tumors." (PMID 38571886, 2024). "Importantly, the rest of the tumor samples, including meningiomas harboring only TRAF7 mutation or together with mutations in genes other than KLF4, had no detectable levels of FGF3 mRNA." (PMID 35996584, 2022). "FGF3 increased proliferation of HBL-52 cells more than 1.5 times on day 7, steadily increased it more by day 12, and doubled it by day 18, suggesting that KLF4K409Q-driven FGF3 expression may enhance meningioma growth." (PMID 35996584, 2022).
metastatic disease (2 papers, 2018 to 2023). "FGFR2 overexpression and FGF3,4,19 gene amplification were seen in primary tumors but not in our series of metastases indicating that these changes play probably a minor role in metastatic disease." (PMID 30181810, 2018).
multiple myeloma (2 papers, 2010 to 2022). "Activation of the fibroblast growth factor 3 (FGFR3) expressed by myeloma cells and its ligand FGF present in the mouse could sustain in vivo angiogenesis such as in the bone marrow milieu." (PMID 20459741, 2010).
Peri-Implantitis (2 papers, 2024 to 2025). An inflammatory process with loss of supporting bone in the tissues surrounding functioning DENTAL IMPLANTS. "The mutations of OPG, BMP-4 and FGF-3 in patients with PI who are heavy smokers or diabetics could explain why these two conditions are risk factors for peri-implantitis." (PMID 38840172, 2024). "The aim was to evaluate the association between single-nucleotide polymorphisms (SNPs) in genes involved in inflammation and bone metabolism (BMP-4, BRINP3, CD14, FGF-3, FGF-10, GBP-1, IL-1α, IL-1β, IL-10, LTF, OPG, and RANKL) and peri-implantitis." (PMID 41373620, 2025).
type 2 diabetes (2 papers, 2024 to 2025). "A significant association of BMP-4 rs17563 and FGF-3 rs1893047 to patients with PI and Type II diabetes mellitus was also identified in our analysis." (PMID 38840172, 2024). "Additionally, the OPG rs2073617 SNP was significant among smokers, and the BMP-4 rs17563 and FGF-3 rs1893047 SNPs were significant among patients with type 2 diabetes." (PMID 41373620, 2025). "When analysing the study groups in relation to risk factors, OPG rs2073617 (p = 0.034) was more frequent in patients with PI who smoked more than 10 cig/day, and BMP-4 rs17563 (p = 0.018) or FGF-3 rs1893047 (p = 0.014) in patients with PI and Type II diabetes mellitus." (PMID 38840172, 2024). "Also, BMP-4 rs17563 (p = 0.018) and FGF-3 rs1893047 (p = 0.014) SNPs were more frequent in patients with PI and Type II diabetes mellitus." (PMID 38840172, 2024).
achondroplasia (1 paper, 2020). Achondroplasia is the most common form of chondrodysplasia, characterized by rhizomelia, exaggerated lumbar lordosis, brachydactyly, and macrocephaly with frontal bossing and midface hypoplasia. "In humans, approximately 70% of cases are caused by spontaneous mutations in fibroblast growth factor 3 resulting in achondroplasia or a milder form of the condition known as hypochondroplasia." (PMID 33090996, 2020).
ameloblastoma (1 paper, 2013). The most common odontogenic tumor, arising from the epithelial component of the embryonic tooth and usually affecting the molar-ramus region of the mandible or maxilla. "We examined 32 cases of ameloblastoma as well as AM-1 cells (an ameloblastoma cell line) and studied the expression of FGF3, FGF7, FGF10 and their specific receptors, namely, FGF receptor (FGFR) 1 and FGFR2." (PMID 24002438, 2013). "In this study, we examined the expression of FGF3, FGF7, FGF10 and their specific receptors in histologically various types of ameloblastoma and analyzed the effect of these growth factors on the proliferation of ameloblastoma using the ameloblastoma cell line AM-1." (PMID 24002438, 2013). "The expression of FGF7, FGF10, FGFR1 and FGFR2 was detected in ameloblastoma cells and AM-1 cells, while that of FGF3 was not." (PMID 24002438, 2013). "In the present study, we thus hypothesized that FGF3, FGF7 and FGF10 may also affect the proliferation of ameloblastoma cells with odontogenic epithelial characteristics and show some evidences that FGF signaling involved in the ameloblastoma proliferation through MAPK pathway." (PMID 24002438, 2013).
benign prostatic hyperplasia (1 paper, 2022). A non-cancerous nodular enlargement of the prostate gland. "Moreover, female mice carrying the transgene of FGF3 cDNA under the control of MMTV LTR sequence developed pronounced mammary gland hyperplasia with a large amount of epithelial tissue in mammary glands, whereas male mice expressing it in the prostate developed benign prostatic hyperplasia." (PMID 35996584, 2022).
carcinoid (1 paper, 2025). "A carcinoid subtype in which SMARCA4, KRAS, FGF3/4/19, STK11, CDKN2A/B, and other genomic alterations predominate in non-small cell lung cancer-like subtypes." (PMID 40661782, 2025).
chondrodysplasia (1 paper, 2024). "Genetic defects in the formation of collagen, proteoglycans, and signal transduction mechanisms such as fibroblast growth factor 3 (FGFR3) deficiency have been identified in several types of chondrodysplasias in humans." (PMID 39061550, 2024).
Cirrhosis (1 paper, 2021). A chronic disorder of the liver in which liver tissue becomes scarred and is partially replaced by regenerative nodules and fibrotic tissue resulting in loss of liver function. "Cirrhosis tended to occur in FGF3 and MUC4 mutation groups (p = 0.019 and 0.011, respectively)." (PMID 35118119, 2021). "However, our results suggested that there were little correlations between gene variations and clinical characteristics except that cirrhosis tended to occur in FGF3 and MUC4 mutation groups." (PMID 35118119, 2021). "Correlations among FGF3 mutation, MUC4 mutation and cirrhosis." (PMID 35118119, 2021).
colon carcinoma (1 paper, 2018). "One FGF3,4,19 amplified colon carcinoma showed an extraordinary high amplification pattern with a FGF-3,4,19/CEN11 ratio of 12.9 and an average gene copy number of 29.9." (PMID 30181810, 2018).
cutaneous melanoma (1 paper, 2020). A primary melanoma arising from atypical melanocytes in the skin. "Moreover, TCGA cutaneous melanoma project has revealed low-frequency pathogenetic mutations in AKT3 (0.3%) and FGF3 (2.5%)." (PMID 33317587, 2020).
Eb (1 paper, 2025). "Based on the expression and functional analyses of fgf3 in Eb formation, we propose a potential role of Fgf3 in developing Eb cartilages." (PMID 40909172, 2025). "Next, we investigated the cellular requirements of Fgf3 in Eb formation." (PMID 40909172, 2025).
Encephalocele (1 paper, 2024). A neural tube defect characterized by sac-like protrusions of the brain and the membranes that cover it through openings in the skull. "In line with the rescue of the encephalocele phenotype, Fgf3 and Fgf4 levels were significantly reduced in the midbrain of ABEs-C4Δ mutants as compared to wildtype littermates or C1-C4Δ mutants." (PMID 39372737, 2024).
glioblastoma (1 paper, 2020). The most malignant astrocytic tumor (WHO grade IV). "As PERK is known to regulate the expression of several angiogenic factors such as VEGF-A, IL6 and FGF3,21, we aimed to identify secreted factors that might be involved in PERK-mediated angiogenesis in glioblastoma." (PMID 32054826, 2020).
hearing loss (1 paper, 2011). "We performed a prospective molecular genetic and clinical study of families segregating hearing loss linked to FGF3 mutations." (PMID 21306635, 2011). "Because of intrafamilial variability, some patients with FGF3-related hearing loss are potential candidates for cochlear implantation, even if CLA has already been documented in other affected family members." (PMID 21306635, 2011).
heart defects (1 paper, 2022). "Furthermore, FGF3 mutations might contribute to congenital heart defects in human." (PMID 36124070, 2022).
hyperparathyroidism (1 paper, 2024). Hyperfunction of the parathyroid glands resulting in the overproduction of parathyroid hormone. "Hyperparathyroidism and persistent elevated circulating FGF3 levels promote renal phosphate wasting and low calcitriol levels." (PMID 39384649, 2024).
Kaposi's sarcoma (1 paper, 2023). A malignant neoplasm characterized by a vascular proliferation which usually contains blunt endothelial cells. "Interestingly, 55% of Kaposi’s Sarcoma, an endothelial tumor, over-express FGF3, thus highlighting the role of FGF3 in angiogenesis." (PMID 36835166, 2023).
lymph node metastasis (1 paper, 2024). "The highest fold change was seen for FGF3 in a lymph node metastasis sample, at 16.4." (PMID 39324009, 2024).
malocclusion (1 paper, 2020). "Our result suggests that genetic polymorphism rs1893047 in FGF3 might contribute to variations in the craniofacial sagittal pattern, specifically to the establishment of the Class III skeletal malocclusion." (PMID 32249341, 2020).
metastatic melanoma (1 paper, 2021). A melanoma that has spread from its primary site to another anatomic site. "Also, amplifications in loci 1p12 (NOTCH2), 3p13 (MITF), 13q13.3 (FGF3/4, CTTN) and 22q13 (MLK1) were found in both cytolytic subtypes of metastatic melanoma." (PMID 33779796, 2021). "CYT-high metastatic melanomas had recurrent copy number amplifications in loci 1p12 (NOTCH2), 1q44 (OR2M4), 7q36.1 (KCNH2), 11q13.3 (FGF3/4), 12p11.23 (MED21) and 12q13.3 (R3HDM2) and deletions in 1p22.1 (RHOC, NRAS), 9p21.3 (CDKN2B), 10q23.2 (miR346), 11q23.3 (ATM, CHEK1, ETS1) and 15q15.3 (CASC4)." (PMID 33779796, 2021).